GCG (glucagon)
Diseases named in the same sentence as GCG in open-access papers (continued):
Sharing a sentence is not in itself a finding about the gene and the disease.
Hypoglycemia (continued). "In summary, available data suggest that in people with type 1 diabetes the loss of glucagon secretion after hypoglycemia is irreversible." (PMID 34405569, 2021). "Incretin therapy slows down gastric emptying, preserves insulin secretion (insulinotropic effects), suppresses glucagon secretion (glucagonostatic effects), and is associated with a much lower risk of hypoglycemia." (PMID 33802091, 2021). "Patients on drugs that increase the risk hypoglycemia should have access to rescue therapies (glucose tablets/gel or glucagon), an adequate supply of testing strips, and immediate access to a member of the health care team." (PMID 34434951, 2021). "Additional in vivo studies showed that V1bR-mediated stimulation of glucagon secretion plays an important role in the counterregulatory hyperglucagonemia triggered by insulin-induced hypoglycemia or glucopenic conditions (deficiency of intracellular glucose)." (PMID 34752420, 2021). "In the setting of T1D, plasma glucagon responses are abnormal; basal levels of glucagon can be high, but glucagon secretion in response to hypoglycemia is often inadequate, increasing the risk for severe hypoglycemia." (PMID 34027090, 2021). "Together these data demonstrate that amplification of the hepatic glucagon signaling pathway is able to rescue hypoglycemia caused by hyperinsulinism." (PMID 32735622, 2020). "Dysregulation of insulin or glucagon can result in loss of blood glucose control, characterized by hyperglycemia or hypoglycemia." (PMID 32296396, 2020). "Their findings suggest that an α-cell-specific induction of mitoNEET, a dimeric mitochondrial membrane protein, perturbs glucagon homeostasis and causes fasting-induced hypoglycaemia." (PMID 32218947, 2020). "While glucagon was found to be effective and reduced hypoglycemia risk in all patients, we observed 1 episode of necrolytic migratory erythema in a patient on high-dose prolonged glucagon infusion therapy." (PMID 33013678, 2020). "Mdg1/ERdj4-deficient mice suffered from hypoglycemia, high glucagon and reduced glycogen production with reduced beta cell levels while alpha cell levels increased." (PMID 32377843, 2020). "In fact, rodent models of T1DM (Bio-Breeder rats and NOD mice), in which an impaired glucagon response to insulin-induced hypoglycemia is also observed, showed an early and selective loss of sympathetic innervation in the islets of Langerhans." (PMID 31620088, 2019). "Symlin (pramlintide) reduces postprandial hypoglycemia by reducing meal-associated glucagon secretion." (PMID 31003482, 2019). "This potential positive effect, however, was marred by research that showed that newer-generation sulfonylureas possessed a lower risk of hypoglycemia and that glibenclamide inhibited glucagon counter-regulation." (PMID 30696060, 2019). "It is unlikely that DPP4 inhibitors cause hypoglycemia when used alone or in combination with metformin, due to the glucose-dependent effects on insulin and glucagon secretion." (PMID 29535389, 2018). "GIP acts as a physiological blood glucose stabilizer associated with stimulation of insulin and glucagon secretion during hyper- and hypoglycemia, respectively, in healthy subjects and in patients with T2D." (PMID 29941634, 2018). "SGLT2 inhibitors, when used alone or in combination with metformin, are also associated with reduced risk of hypoglycemia by increasing plasma glucagon concentrations and decreasing plasma insulin concentrations." (PMID 29535389, 2018). "Consistent with this, glucagon responses to hypoglycemia were also increased in I366F mice with mutated glucokinase and in streptozotocin-treated β-cell ablated diabetic I366F mice." (PMID 30146176, 2018). "DPP4i drugs also have a minimal risk of hypoglycemia due to their glucose-dependent mechanism of action regarding the regulation of insulin and glucagon secretion." (PMID 29511288, 2018).
Hypoglycemia (continued). "SSTR2 antagonism after recurrent hypoglycemia ameliorates the glucagon and corticosterone responses, as well as decreases the risk of insulin-induced hypoglycemia in rats with type 1 diabetes." (PMID 29342932, 2018). "For example, loss of the KATP channel subunit, KIR6.2, causes near complete suppression of glucagon responses to hypoglycemia, which is driven by the loss of KATP on neural cells." (PMID 28087336, 2017). "Lack of paracrine inhibition of the α-cells is often considered to underlie glucagon hypersecretion in diabetic hyperglycaemia, and paracrine factors have also been implicated in glucose control of glucagon secretion in hypoglycaemia." (PMID 27044660, 2016). "Type 1 diabetes patients with defective glucagon and adrenaline response to hypoglycaemia have a 25-fold or greater increased risk of iatrogenic hypoglycaemia during intensive insulin therapy." (PMID 27843452, 2016). "Patients with type 1 or severe type 2 diabetes are at high risk of life-threatening hypoglycemia, due to a combination of intensive insulin treatment and impaired glucagon secretion." (PMID 24616659, 2014). "On the other hand, the condition of hyperinsulinemia associated with hypoglycemia leads to the activation of the counterregulatory system with intensification of the release of glucagon and epinephrine." (PMID 24062772, 2013). "Injection of STZ selectively destroys beta cells, leaving the glucagon producing alpha cells intact and thus lessening the risk of hypoglycemia." (PMID 22390349, 2012). "Although effective in reducing the risk of hypoglycemia, glucagon cannot be fully relied upon to reverse the effect of insulin overdelivery." (PMID 22071283, 2011). "Due to the difficulties associated with detecting nocturnal hypoglycemia, a long-lasting prophylactic form of glucagon would be preferred." (PMID 20418955, 2010). "Interestingly, the post-RYGB change of hypothalamic and frontal cortex glucose uptake rate was associated with altered glucagon secretion during hypoglycemia after surgery." (PMID 39644424, 2025). "They hypothesized that SGLT2i could induce glucagon release from pancreatic alpha islet cells, which could ameliorate the risk of severe hypoglycemia." (PMID 40933374, 2025). "Similarly, diabetes in animal models is associated with impaired glucagon secretion in response to hypoglycemia; an event corrected by somatostatin receptor antagonists." (PMID 40473678, 2025). "In contrast to glucagon, its stability in aqueous solutions allows for ready-to-use formulations and continuous subcutaneous infusion, simplifying management and reducing the risk of rebound hypoglycemia." (PMID 40300042, 2025). "The outpatient treatment of severe hypoglycemia in T1D, involving loss of consciousness and/or the inability to swallow, principally involves the administration of intramuscular, subcutaneous or intranasal glucagon." (PMID 39944479, 2024). "Severe hypoglycemia is an event associated with severe cognitive impairment (including loss of consciousness and seizures) that requires the assistance of another person to administer intravenous carbohydrates, glucagon, or glucose." (PMID 38894740, 2024). "When used concurrently with indomethacin, glucagon may lose its ability to increase blood glucose levels and could potentially cause hypoglycemia." (PMID 39199604, 2024). "CFTR gene mutations may also diminish glucagon release from pancreatic α-cells, resulting in an insufficient response to hypoglycemia." (PMID 38541202, 2024). "Patients undergoing diagnostic glucagon administration may experience discomfort, particularly if fasting, manifesting as nausea, hypoglycemia, or changes in blood pressure." (PMID 39199604, 2024). "Proposed mechanisms of hypoglycemia associated with opioid use are endogenous hyperinsulinemia, hypoadrenalism, reduced hepatic hypoglycemia, suppression of counter-regulatory hormones, glucagon, and epinephrine." (PMID 39040763, 2024).
Hypoglycemia (continued). "Taken together, these data show an association between RAGE and GCG expression in the α cells in type 1 diabetes, in which there was an inverse correlation in a donor with documented hypoglycemia as well as in adolescents who are clinically at higher risk of this potentially lethal complication." (PMID 37558746, 2023). "However, in patients with type 1 diabetes, there is a progressive loss of glucagon response to insulin-induced hypoglycemia." (PMID 36769430, 2023). "Deficiency in glucagon production precipitates hypoglycemia unawareness." (PMID 37933577, 2023). "DPP-4 inhibitors do not cause weight gain compared with the impact of a rapid decrease in blood glucagon, and because they act dependently on blood glucagon concentrations in the body, they have a low risk of hypoglycemia and are used as an adjuvant to dietary and exercise therapy." (PMID 37111730, 2023). "As a consequence, patients with VLCAD deficiency—and to a lesser extent patients with MCAD deficiency—could have low plasma glucagon concentrations, possibly contributing to their tendency to develop hypoglycemia during prolonged fasting." (PMID 37512487, 2023). "Initially, we hypothesized that the addition of glucagon could have counteracted the increased risk for hypoglycemia during physical activity." (PMID 36755913, 2023). "Two studies claimed that Irak4 (Interleukin-1 receptor associated kinase-4) controls hypoglycemia-induced glucagon secretion by modulating hypothalamic Il-1β signaling, and Agpat5 activation in AgRP (agouti-related protein) neurons leads to hypoglycemia-induced glucagon secretion." (PMID 37764697, 2023). "However, in T1DM, hypoglycemia is caused by excessive exogenous insulin injection, involving low glycemia and high insulinemia that blocks glucagon release." (PMID 37998439, 2023). "Furthermore, around exercise the risk of hypoglycemia is higher due to increased insulin sensitivity, insulin absorption, glucose uptake in combination with an impaired glucagon secretion." (PMID 36755913, 2023). "Similarly, plasma glucagon concentrations are suppressed during exercise in people with type 1 diabetes (T1D) thus increasing their risk for hypoglycemia." (PMID 35590248, 2022). "Moreover, their intrinsic effects on insulin and glucagon are tailored in a glucose-dependent manner, thus posing a low risk of hypoglycemia and making them one of the most effective and safest options when a more intensive antidiabetic treatment is required." (PMID 35429298, 2022). "A potential explanation may be a protective effect of glucagon against acute hypoglycemia to counterbalance a strong insulin response to the glucose load and genetic variants involved in ion-channels regulating glucagon secretion." (PMID 36686477, 2022). "Insufficient glucagon during hypoglycemia may increase risk of acute shock, while inappropriately elevated post-prandial glucagon may exacerbate hyperglycemia." (PMID 36277717, 2022). "This large variability in glycaemic thresholds in type 1 diabetes can probably be explained by different prior hypoglycaemia exposure rates between individuals, the loss of glucagon secretion within years after diagnosis, blunted catecholamine responses and impaired hypoglycaemic awareness." (PMID 35867127, 2022). "In the case of an unclear cause of hypoglycaemia, a glucagon test is performed." (PMID 36294341, 2022). "However, in the afternoon (~16:00-17:00), growth hormone and cortisol decline, thereby increasing the risk of hypoglycaemia, as gluconeogenesis and glucagon concentration decrease, respectively." (PMID 36246914, 2022). "In addition, there is inadequate plasma glucagon concentration in response to declining plasma glucose levels in the late post-prandial period increasing the risk for and delayed recovery from hypoglycemia." (PMID 35590248, 2022). "The addition of glucagon or other adjuncts to mitigate the risk of hypoglycemia?" (PMID 35733769, 2022).
Hypoglycemia (continued). "Blockade of GLP-1 action through intravenous Ex-9 in individuals with PHH reduced postprandial insulin secretion by around 50–70%, increased the glucagon levels, increased the postprandial glucose levels (including the nadir glucose levels) and reduced the risk and symptoms of hypoglycaemia." (PMID 33652862, 2021). "Loss of glucagon response to hypoglycemia in people with T1DM appears to be a “selective” decreased response of the α cells to glucose stimulus, as the response to non-glucose stimuli such as the amino acids arginine, alanine, and a mixture of amino acids is largely maintained." (PMID 34572493, 2021). "Two main hypotheses proposed for loss of appropriate glucagon secretion during hypoglycemia include loss of sympathetic innervation to stimulate islet glucagon secretion and intrinsic defects in α-cells, either primary or secondary to loss of islet β-cells." (PMID 33753784, 2021). "In addition, after experiencing a bout of hypoglycemia, patients become even more susceptible to developing hypoglycemia because of further diminished counterregulatory hormone secretion, including glucagon." (PMID 34003799, 2021). "On top of that, it might be that the patients on the LCD are at increased risk of severe hypoglycemia as their response to glucagon is blunted." (PMID 34836158, 2021). "Patients with liver cirrhosis may have dysfunction in gluconeogenesis and shortage of glycogen storage, reduced metabolism of antidiabetic drugs, impaired glucagon catabolism and increased risk of hypoglycemia." (PMID 33315940, 2020). "Finally, impaired counter‐regulatory glucagon secretion with the risk of severe (potentially fatal) hypoglycaemia represents a barrier towards optimal glycaemic control." (PMID 32716554, 2020). "However, in our study, an even earlier glucagon response 15 min after the meal was associated with lower rates of postprandial hypoglycemia, suggesting a protective role against hypoglycemia." (PMID 33424773, 2020). "Studies in T1DM have shown that in addition to causing hyperglycemia through increased level of glucagon, α cell dysfunction may also result in insufficient glucagon release in situation of hypoglycemia." (PMID 33250773, 2020). "We hypothesized that amplification of the glucagon signaling pathway could ameliorate hyperinsulinism associated hypoglycemia." (PMID 32735622, 2020). "Other potentially predisposing risks for hypoglycemia include impaired or loss of glucagon response to hypoglycemia in long-standing T1DM, increased risk of celiac disease, and increased risk of hypoadrenalism due to the predisposition of a shared autoimmune background." (PMID 31866948, 2019). "The risk of hypoglycaemia is increased for diabetics, due to either an impaired response of the alpha cells in the pancreas, or as a side effect of insulin therapy and can require an additional supply of exogenous glucagon to be administered." (PMID 31829209, 2019). "Impaired glucagon secretion in patients with diabetes causes hypoglycemia." (PMID 30635569, 2019). "In summary, these data support the hypothesis that a fixed ratio of insulin and a long‐acting glucagon‐analogue can reduce the risk of hypoglycemia." (PMID 29595915, 2018). "Our data identify a GCK-dependent glucose-sensing mechanism during hypoglycemia that boosts responses to falling glucose; augmenting hypoglycemia-associated reduction in insulin secretion and the release of the counter-regulatory hormones glucagon and epinephrine." (PMID 30146176, 2018). "Our goal was to find a fixed ratio of glucagon and insulin which could combine the ability to normalize blood glucose with reduced risk of hypoglycemia in diabetic rats." (PMID 29595915, 2018). "The use of a simplified meal bolus strategy is possibly best accompanied with glucagon to prevent hypoglycemia risk, especially during the late postprandial phase, but investigating this strategy in the context of single-hormone closed-loop delivery would be of interest." (PMID 29422651, 2018).
Hypoglycemia (continued). "In addition, we have recently shown that treatment with a fixed 1:23 ratio of a long-acting glucagon analog and insulin reduced the acute risk of hypoglycemia in streptozotocin (STZ) induced diabetic rats." (PMID 29558502, 2018). "Further reduction of hypoglycaemia risk might be achieved through the addition of glucagon in bihormonal closed-loop systems, particularly during exercise." (PMID 30292578, 2018). "Thus, several studies have shown a beneficial effect of glucagon in reducing the risk of hypoglycemia in insulin therapies." (PMID 29595915, 2018). "Glucagon is a counter regulatory hormone and we hypothesize that a fixed ratio of insulin and a long‐acting glucagon‐analogue can reduce the risk of hypoglycemia." (PMID 29595915, 2018). "Thus, acute septic shock causes hypoglycemia via induction of glucagon resistance, while chronic low-grade inflammation leads to hyperglycemia via induction of insulin resistance." (PMID 27990298, 2016). "Combination of glucagon inhibition with insulin therapy may however increase the risk of hypoglycemia." (PMID 27092792, 2016). "It is well established that glucagon secretion in T1D is impaired, and there is further strong evidence from closed loop delivery systems that bi-hormonal delivery of insulin and glucagon has been shown to reduce the risk of hypoglycaemia when compared with delivery of insulin alone." (PMID 24481872, 2014). "We propose that aberrant glucagon secretion may underlie hypoglycemia in mice with VHL loss in neonatal islets." (PMID 23977255, 2013). "The in silico results demonstrate that the proposed bihormonal AP systems have outstanding superiorities in reducing the risk of hypoglycemia, smoothing the glucose level, and robustness with respect to insulin/glucagon sensitivity variations, compared with the optimal unihormonal AP system." (PMID 24260042, 2013). "In agreement with this hypothesis, several studies have linked impaired α-cell formation or glucagon production to severe hypoglycemia and associated neonatal lethality." (PMID 23977255, 2013). "The lower risk of hypoglycemia with liraglutide administration may be explained by its stimulation of insulin release and glucagon suppression in a glucose-dependent manner." (PMID 23153177, 2012). "However, reports of hypoglycemia—especially in patients previously on insulin—suggest that modulators may also alter glucagon secretion, raising the risk of hypoglycemia in CFRD." (PMID 41552835, 2026). "However, individuals with advanced or long-standing T2D may also have glucagon counterregulatory deficiency to hypoglycemia." (PMID 38510652, 2024). "Indeed, evidence suggests that sitagliptin and other DPP-4is are able to reduce daily insulin requirements and improve glucose control without increasing the risk of hypoglycemia or compromising the glucagon counterregulatory response during hypoglycemia in patients with T1D." (PMID 37249465, 2023). "CH could be classified into focal or diffuse forms and is characterized by increased insulin secretion by pancreatic beta-cells, causing hypoglycemia associated with low/normal levels of ketones and fatty acids, absence of metabolic acidosis, and positive glycemic response to glucagon." (PMID 37630734, 2023). "However, in a situation where a patient presents with severe hypoglycemia, the acute risk must be managed immediately, and in this situation the benefits of glucagon treatment could outweigh the risks." (PMID 37512487, 2023). "Thus, GIP′s role in improving glucagon counter-regulation may further contribute to reducing the risk of hypoglycemia associated with DPP4i." (PMID 35630534, 2022). "Although the glucagon response is probably retained in adults with a short duration of type 1 diabetes, contributing to their often good glycaemic control combined with low hypoglycaemia risk, it is almost universally lost within the first few years after diagnosis." (PMID 35867127, 2022).